USP50 (ubiquitin specific peptidase 50)
Description:
Deubiquitinating enzyme that removes conjugated ubiquitin from specific proteins to regulate different cellular processes. Regulates the inflammasome signaling pathway by deubiquitinating 'Lys-63'-linked polyubiquitination of the PYCARD/ASC adapter protein. Regulates the ubiquitination and stability of the ACE2 protein. Acts as a negative regulator of the G2/M checkpoint pathway, by preventing serine/threonine kinase WEE1 degradation, thereby repressing entry into mitosis following activation of the G2/M DNA damage checkpoint.
Tractability: No criterion of Open Targets' tractability assessment is met for any kind of drug.
Gene: Protein-coding gene on chromosome 15 (50,494,018 to 50,546,708, reverse strand). Ensembl gene ENSG00000170236.
Subcellular location: Cytoplasm; Cytoplasm, cytoskeleton, microtubule organizing center, centrosome; Nucleus
Gene Ontology:
Molecular function: cysteine-type deubiquitinase activity; ubiquitin-like protein peptidase activity; cysteine-type peptidase activity
Biological process: nuclear speck organization; positive regulation of interleukin-1 beta production; positive regulation of NLRP3 inflammasome complex assembly; protein deubiquitination; regulation of cell cycle G2/M phase transition; endosome organization; Ras protein signal transduction
Cellular component: centrosome; cytoplasm; nucleus; cytosol; midbody; postsynaptic density
Genetic constraint (gnomAD): Loss-of-function variants: 39 observed, 40.17 expected, observed/expected ratio (o/e) 0.97, 90% interval 0.75 to 1.27. The upper end of that interval is the gene's LOEUF score, 1.27, which puts it in group 5 of 6, group 1 being the genes least tolerant of losing a copy. Missense variants: 374 observed, 411.38 expected, observed/expected ratio (o/e) 0.91, 90% interval 0.83 to 0.99. Synonymous variants: 139 observed, 148.7 expected, observed/expected ratio (o/e) 0.93, 90% interval 0.81 to 1.08.
Homologues: Orthologues: macaque USP50 (88% identical), rabbit USP50 (88% identical), pig USP50 (84% identical), dog USP50 (82% identical), rat Usp50 (79% identical), chimpanzee USP50 (78% identical), mouse Usp50 (78% identical), guinea pig USP50 (73% identical). Paralogues in human: USP8 (38% identical), USP15 (31% identical), USP2 (30% identical), USP4 (30% identical), USP31 (28% identical), USP43 (28% identical), USP11 (28% identical), USP32 (28% identical), USP33 (27% identical), USP44 (26% identical), USP6 (26% identical), USP21 (26% identical), and 59 more.
Diseases named in the same sentence as USP50 in open-access papers:
USP50 is named in the same sentence as 7 diseases in open-access papers, as found by Europe PMC text mining. Sharing a sentence is not in itself a finding about the gene and the disease. The quoted sentences say what the papers report.
gastric cancer (2 papers, 2024). A primary or metastatic malignant neoplasm involving the stomach. "It should be noted that other DUBs (such as USP50, USP51, USP52, JOSD3, and UAF1), which were identified to potentially regulate RBM39 in the biochemical screening, neither have high mRNA expression in gastric cancer tissues nor affect the overall patient survival based on the database analysis." (PMID 39260689, 2024).
breast carcinoma (1 paper, 2024). "We also noted that USP50 siRNA treatment of the human breast cancer cell line MCF7 also increased 53BP1 foci numbers, as did the treatment of mouse NIH3T3 cells with siRNA targeting murine USP50." (PMID 39284827, 2024).
colon cancer (1 paper, 2024). "We wondered whether USP50 contributes to this activity and tested MSI-H colon cancer cell lines, HCT116 and RKO, for sensitivity to USP50 siRNA." (PMID 39284827, 2024).
Sepsis (1 paper, 2025). Sepsis is defined as life-threatening organ dysfunction caused by a dysregulated host response to infection. "For instance, mitochondrial STAT3 can trigger fatty acid oxidation by inducing the stabilization of CPT1a mediated by USP50 in macrophages, exacerbating LPS-induced sepsis." (PMID 40766066, 2025).
tumor (1 paper, 2024). "The tumor-inhibitory effect of USP50 depletion was reversed by rhHMGB1." (PMID 38469295, 2024). "Furthermore, enhancing USP50 expression in macrophages accelerated the promoting effect of TDCA-CM on the aggressive behavior of tumor cells, which was abolished by HMGB1 neutralizing Abs." (PMID 38469295, 2024).
USP50 also shares sentences with these, for which no sentence is quoted: COVID-19 (1 paper); duodenogastric reflux (1).